BORCS8 (BLOC-1 related complex subunit 8)
Description:
As part of the BLOC-one-related complex (BORC), it plays a role in the movement and localization of lysosomes at the cell periphery. Associated with the cytosolic face of lysosomes, BORC recruits ARL8B to the lysosomal membrane and couples lysosomes to microtubule plus-end-directed kinesin motors, driving lysosome movement toward the cell periphery.
Synonyms: MEF2BNB; NDOABA
Tractability: PROTAC: ubiquitination databases record sites on it.
Gene: Protein-coding gene on chromosome 19 (19,176,902 to 19,192,591, reverse strand). Ensembl gene ENSG00000254901.
Subcellular location: Lysosome membrane
Subcellular location (Human Protein Atlas): Vesicles
Gene Ontology:
Molecular function: protein binding
Biological process: heart development; lysosome localization; organelle transport along microtubule; regulation of endosome size; regulation of lysosome size
Cellular component: BORC complex; cytoplasmic side of lysosomal membrane; lysosomal membrane
Genetic constraint (gnomAD): Loss-of-function variants: 13 observed, 18.71 expected, observed/expected ratio (o/e) 0.69, 90% interval 0.45 to 1.1. The upper end of that interval is the gene's LOEUF score, 1.1, which puts it in group 4 of 6, group 1 being the genes least tolerant of losing a copy. Missense variants: 165 observed, 167.02 expected, observed/expected ratio (o/e) 0.99, 90% interval 0.87 to 1.12. Synonymous variants: 68 observed, 65.89 expected, observed/expected ratio (o/e) 1.03, 90% interval 0.85 to 1.26.
Homologues: Orthologues: dog BORCS8 (98% identical), mouse Borcs8 (94% identical), pig BORCS8 (92% identical), guinea pig BORCS8 (87% identical), chimpanzee BORCS8 (82% identical), rat Borcs8 (81% identical), zebrafish borcs8 (71% identical), tropical clawed frog borcs8 (62% identical), Drosophila melanogaster CG32590 (25% identical), Caenorhabditis elegans blos-9 (24% identical).
Diseases named in the same sentence as BORCS8 in open-access papers:
BORCS8 is named in the same sentence as 2 diseases in open-access papers, as found by Europe PMC text mining. Sharing a sentence is not in itself a finding about the gene and the disease. The quoted sentences say what the papers report.
COVID-19 (1 paper, 2024). A disease caused by infection with severe acute respiratory syndrome coronavirus 2. "In this work, we identified an increased expression of lysosomal genes such as LAMTOR1, NEU1, GBA1, BORCS8, and BLOC1S1 in severe COVID-19 patients." (PMID 38262689, 2024).
BORCS8 also shares sentences with these, for which no sentence is quoted: Cerebral atrophy (1 paper).